SOD3 (superoxide dismutase 3)
Diseases named in the same sentence as SOD3 in open-access papers (continued):
Sharing a sentence is not in itself a finding about the gene and the disease.
cancer (continued). "In contrast to the case in benign growth, SOD3 expression is progressively downregulated in a number of cancers and cancer cell lines, correlating with the RAS activation level, which suggests that sod3 could be a prognostic differentiation marker." (PMID 27293512, 2016). "Although methylation changes are observed even in precancerous stages with chronic inflammation, the current data suggest the most prominent role for methylation-mediated SOD3 silencing in the presence of high RAS activity in advanced well-differentiated and poorly differentiated aggressive cancers." (PMID 26550576, 2015). "Decreased expression of SOD3 were found in TPC1 cells modeling PTC whereas MSCs isolated from PTC exhibited increased expression of SOD3 than MSCs isolated from non-carcinogenic thyroids (Thyroid MSCs), thus suggesting the role of SOD3 in regulating cancer progression." (PMID 32128111, 2020). "If confirmed, the cell type-specific SOD3 effect on HIF-2α levels might be of therapeutic use, given the antithetical HIF-2α function in tumorigenesis; its upregulation in cancer cells promotes proliferation and neoangiogenesis and, in ECs, induces vascular normalization and enhanced drug delivery." (PMID 29422508, 2018). "Correspondingly, RNAi SOD3 treatment of PTC MSCs decreased (p < 0.001) TPC1 DNA replication compared to parental PTC MSCs, thus demonstrating that PTC MSCs may support cancer cell growth by secreting SOD3." (PMID 28216675, 2017). "Although the function of SOD3 as a regulator of cellular growth has been well established by a number of studies, the enzyme itself might not be a suitable cancer drug or druggable target molecule." (PMID 27293512, 2016). "Functionally, supraphysiological overexpression of SOD3 inhibits the nuclear localization of NF-κB, reduces VEGF-A expression, decreases cell proliferation, inhibits tumor growth, decreases metastasis (suggesting a reduction of in vivo cancer cell migration), and increases apoptosis." (PMID 27293512, 2016). "We observed that SOD3 expression in the tumor stromal cells was different among the subtypes of OSCC, although the cancer area showed no expression." (PMID 36359248, 2022). "Thus, SOD3, by affecting local ROS concentrations, might have progrowth characteristics in early tumorigenesis as a mediator of the RAS oncogene and, in certain cellular environments, may work in coordination with other growth factors that stimulate cancer cell proliferation." (PMID 27293512, 2016). "Correspondingly, SOD3 (ρ=-0.36, p < 0.001) showed the strongest negative correlation with Cu abundance within this pathway, suggesting that elevated Cu levels may drive downregulation of this protective gene through upregulation of ATP7A, further promoting cancer aggressiveness." (PMID 41042257, 2025).
tumor (53 papers, 2010 to 2026). "Re-expression of SOD3 in tumor-associated endothelial cells induces perivascular nitric oxide accumulation and reduces vessel leakage by up-regulating vascular endothelial cadherin (VE-cadherin) expression, thereby enhancing tumor response to chemotherapy." (PMID 41028519, 2025). "The negative regulation of SOD3 in a tumor is associated with its progression through the pro-oncogenic NF-κB and HIF-1α signaling pathways, as has been observed." (PMID 39589950, 2024). "These suggest that the loss of intracellular expression of SOD3 promotes a microenvironment conducive to tumor growth by giving a selective advantage to tumor cells." (PMID 39589950, 2024). "The rate of allelic deletion increases drastically between cervical intraepithelial neoplasia and grade I cervical cancer, suggesting that SOD3 downregulation is associated with tumor progression." (PMID 33250894, 2020). "At ultrastructural level, SOD3 causes smoothness of the vessel lumen, consistent with enhanced EC quiescence, reduces vascular permeability, and improves tumor perfusion." (PMID 33250894, 2020). "The SOD3 gene encodes an extracellular isoform of the enzyme, and data suggest that SOD3 acts as a tumor suppressor in PC." (PMID 33552133, 2020). "Here we show that specific SOD3 re-expression in tumor-associated endothelial cells (ECs) increases doxorubicin (Doxo) delivery into and chemotherapeutic effect on tumors." (PMID 29422508, 2018). "In the TMA analyses of CRC patients, individual tumor-associated ECs accumulated intracellular/nuclear SOD3." (PMID 29422508, 2018). "Ad-mSOD3 also enlarged the extension of VEC junctions compared to Ad-C (Ad-mSOD3, 7.1 ± 1.6 μm, n = 50; Ad-C, 2.9 ± 0.5 μm, n = 81; p < 0.05, two-tailed Student’s t-test), which indicates that SOD3 directly regulates VEC expression in tumor-associated ECs." (PMID 29422508, 2018). "We demonstrate that Nrp2 is the VEGF-C-associated receptor that mediates alterations in Sod3 expression and the response of tumor cells to oxidative stress." (PMID 25358638, 2014). "The presence of M2-like macrophages is linked to a more aggressive tumor phenotype, and targeting SOD3 could potentially modulate the immune environment to favor anti-tumor responses." (PMID 41009025, 2025). "Furthermore, it has been demonstrated that the expression of SOD3 enhances therapeutic response in tumor-associated endothelial cells." (PMID 39589950, 2024). "Lov treatment might thus have additional, SOD3-independent effects on tumor perfusion, possibly linked to its pleiotropic activities on the endothelium." (PMID 29422508, 2018). "Knockdown of SOD3 decreases the M2-like pro-tumoral transformation of macrophages both in vitro and in vivo, suggesting SOD3’s potential role in regulating macrophage M2-like pro-tumoral transformation, which is associated with immunosuppression and tumor progression." (PMID 41009025, 2025). "SOD3 also participates in the epigenetic mechanism of methylation, where a predominantly downregulated expression pattern of SOD3 and various genetic and epigenetic deregulations suggest that the loss of this antioxidant promotes a microenvironment advantageous for tumor development in BC." (PMID 39589950, 2024). "Elevated SOD1 and SOD2 levels often promote oncogenic signalling and tumour survival, whereas SOD3 exhibits context-dependent roles, balancing tumour suppression and progression." (PMID 41799710, 2026). "PRDX2, PKD2 (polycystin-2), and AQP1 were overexpressed in tumor tissues, whereas SOD3 and KLF2 were downregulated." (PMID 41140697, 2025). "Recent studies have identified SOD3 as a tumor suppressor gene that inhibits tumor development in colorectal, gastric, and pancreatic cancer." (PMID 41028519, 2025). "Through scRNA-seq and immunohistochemical analysis of clinical samples, we show that CAFs mainly produce SOD3 in the LUAD tumor microenvironment." (PMID 41028519, 2025).
tumor (continued). "Unlike previous studies, our research identifies CAFs as the primary source of SOD3 production in the LUAD tumor microenvironment." (PMID 41028519, 2025). "Extracellular superoxide dismutase (SOD3) is an antioxidant enzyme that regulates oxidative stress and is regarded as a tumor suppressor." (PMID 41028519, 2025). "LUAD tumors with high SOD3 expression exhibited a higher incidence of intralymphatic tumor invasion." (PMID 41028519, 2025). "Consistent with the in vitro observations, we confirmed that tumor cells of the SOD3-overexpressed CAF co-transplantation group exhibited a higher expression of N-cadherin than the other groups." (PMID 41028519, 2025). "This epigenetic modification contributes to reduced SOD3 levels, potentially promoting tumor progression." (PMID 40558258, 2025). "Other reports have indicated that high SOD3 expression in endothelial cells enhances laminin α4 production, which selectively increases T-cell infiltration into the tumor." (PMID 41028519, 2025). "It has been shown that the specific re-expression of SOD3 in tumor endothelial cells (VEC and HIF-2α) increases the delivery of doxorubicin and enhances the chemotherapeutic effect in tumors." (PMID 39589950, 2024). "Herein, we found SOD3 downregulation in tumor tissues and its downregulation predicted poor outcomes in CRC." (PMID 39128081, 2024). "Then, the SOD3 protein level in 8 pairs of randomly chosen CRC tumor and adjacent normal tissues was measured through western blotting." (PMID 39128081, 2024). "Concerning the regulation process of oxidative stress in the tumor microenvironment, different cellular mechanisms related to the participation of SOD3 have been proposed." (PMID 39589950, 2024). "Changes in subcutaneous tumor and liver nodule size after SOD3 overexpression were examined in nude mice." (PMID 39128081, 2024). "On the other hand, it has been noted that circulating levels of SOD3 increase when BC patients respond to treatment with a reduction in tumor size during neoadjuvant chemotherapy." (PMID 39589950, 2024). "For example, SOD3, specific to fibroblasts in most tumours, is expressed at high levels in normal epithelial cells and stellate cells but suppressed in malignant cells of PAAD, associated with the promotion of an aggressive phenotype." (PMID 39393173, 2024). "In CRC patients, SOD3-low expression was significantly related to T and N stages and tumor differentiation." (PMID 39128081, 2024). "Superoxide dismutase 3 upregulation attenuates tumor growth and liver metastasis in colorectal cancer, suggesting that SOD3 has potential diagnostic and prognostic values regarding colorectal cancer treatment." (PMID 39128081, 2024). "The results showed that SOD3 differentially regulates laminin-α4 and laminin-α5 in the tumor endothelium." (PMID 35267534, 2022). "In apparent contradiction, whereas SOD3 enhances tumor infiltration of effector T cells in the TME by changing the laminin α4/α5 balance, also reduces the expression of endothelial adhesion molecules required for leukocyte diapedesis." (PMID 35267534, 2022). "Like microarray data, SOD3 expression was higher in the stromal area of the HSC-2+VSCC tumor than that in the HSC-2+SCC tumor." (PMID 36359248, 2022). "SOD3 promoted notable transcriptomic changes in tumor-stimulated endothelial cells, including the inhibition of the nuclear factor kappa B (NF-κB) pathway, an inductor of laminin α5 transcription." (PMID 35267534, 2022). "Further research is needed to clarify the role of SOD3 on ICAM-1 transcription in the tumor endothelium." (PMID 35267534, 2022). "In conclusion, SOD3 is a major regulator of laminin balance in the basement membrane of tumor ECs, with potential implications for immune cell infiltration into tumors." (PMID 35267534, 2022). "For more knowledge to understand how stromal cells regulate SOD3 expression and tumor vascularization, further studies are needed to investigate." (PMID 36359248, 2022).
tumor (continued). "Restoration of antioxidant, SOD3, provides the normalization of tumor vessels and improves the delivery of chemotherapeutics into the tumor." (PMID 36359248, 2022). "The present work suggests that the antioxidant enzyme SOD3 is a negative regulator of laminin α5 expression in tumor ECs." (PMID 35267534, 2022). "SOD3 expression in endothelial cells enhances vasorelaxation, regulates VE-cadherin expression, and enhances the tumor response to chemotherapy." (PMID 36359248, 2022). "We show now that SOD3 overexpression in neoplastic and endothelial cells (ECs) reduces laminin α5 in tumor blood vessels." (PMID 35267534, 2022). "Now that we know that tumor cells with low SOD3 expression are more likely to be killed by chemotherapy drugs, we can apply the theory to clinical use." (PMID 35356201, 2022). "According to the result of western blot, the expression of SOD3 in tumor cells was higher than that in normal cells." (PMID 35356201, 2022). "Consistent with this, tumor tissue of the HSC-2+VSCC xenograft showed a higher expression of SOD3 than the HSC-2+SCC xenograft." (PMID 36359248, 2022). "Then, by comparing the expression of 24 immune-related cells in the tumor microenvironment, we found that the tumor microenvironment of samples from patients with high SOD3 expression had higher immune cells." (PMID 35356201, 2022). "The present work also identifies a complex transcriptional program under the control of SOD3 in ECs, responsible for the normalization of the tumor vasculature." (PMID 35267534, 2022). "SOD3 function can exert an effect opposite to that of the cysteine/glutamate transporter in the control of the redox state of the tumor microenvironment." (PMID 34943029, 2021). "For example, extracellular superoxide dismutase (SOD3) is a secretase that regulates the balance of redox reactions in tissues and regulates tumor vascular distribution in tumors, increasing the sensitivity of tumors response to chemotherapy." (PMID 33754068, 2021). "Inhibition of tumor cell reproduction and migration and invasion of other tissues in PC-3 cells occurred with either SOD3 overexpression or use of recombinant SOD3." (PMID 34943029, 2021). "One of the most striking findings is that SOD3 induces the specific intra-tumor infiltration of effector T-cells." (PMID 33250894, 2020). "SOD3 also has anti-tumor effects by altering the structure, composition, and dynamics of the extracellular matrix." (PMID 33250894, 2020). "SOD3 thus creates an immunogenic TME that significantly reduces tumor growth and improves immunotherapy." (PMID 33250894, 2020). "Our data also demonstrate that SOD3 gene expression was increased relative to time to relapse and was lower in tumor samples from patients with an unfavorable prognosis." (PMID 33552133, 2020). "This review highlights new data suggesting the antioxidant enzyme superoxide dismutase-3 (SOD3) to be a regulator of EC-BM composition in the tumor vasculature." (PMID 33250894, 2020). "The upregulation of SOD3 in the tumor stroma makes the tumor endothelium more permissive to adoptively transferred and endogenous tumor-specific CD4+ and CD8+ T-cells." (PMID 33250894, 2020). "Virus-mediated gene transfer of SOD3 to restore the expression of the enzyme is correlated with increased primary tumor growth and metastasis levels." (PMID 29478325, 2019). "Again, the variation among individuals nullifies the general conclusions of the expression levels; therefore, the effect of SOD3 in tumor progression cannot be generalized using patient expression data alone." (PMID 29478325, 2019). "SOD3 and HIF-2α nonetheless correlated positively in CRC tumor stroma but were negatively associated in tumor epithelial cells, which suggests that SOD3 stabilizes HIF-2α specifically in stromal but not in neoplastic cells." (PMID 29422508, 2018). "Extracellular superoxide dismutase (SOD3) is an antioxidant enzyme usually repressed in the tumor milieu." (PMID 29422508, 2018).
tumor (continued). "SOD3EC-Tg tumor vessels were larger and of greater diameter than those in control mice, whereas vessel branching was unaffected by SOD3." (PMID 29422508, 2018). "Here we identify SOD3 upregulation as a target for improving tumor perfusion and selective Doxo delivery through increased VEC transcription via HIF-2α." (PMID 29422508, 2018). "SOD3 overexpression in ECs was sufficient to increase Doxo effectiveness and reduce tumor vessel permeability, although we observed similar effects after intratumor injection of Ad-mSOD3, which infects and triggers SOD3 expression in tumor and stromal cells." (PMID 29422508, 2018). "We used three approaches to upregulate SOD3 in the in vivo tumor environment, one pharmacological (Lov administration) and two genetic (intratumor Ad-mSOD3 injection and EC-specific inducible SOD3 expression)." (PMID 29422508, 2018). "Pharmacological or genetic SOD3 upregulation in the tumor environment thus increased levels of the small compound Doxo in tumors." (PMID 29422508, 2018). "In summary, our results identify SOD3 as a regulator of VEC transcription in tumor vasculature by NO-dependent stabilization of HIF-2α." (PMID 29422508, 2018). "Here we used pharmacological and genetic approaches to determine that restoration of SOD3 levels in tumors regulates tumor vasculature and increases the tumor response to chemotherapy." (PMID 29422508, 2018). "Compared to the weak SOD3 staining in Ad-C (β-galactosidase-encoding)-injected tumors, Ad-mSOD3 injection notably increased SOD3 staining in tumor and stromal cells." (PMID 29422508, 2018). "Blood vessel labeling with fluorescein isothiocyanate (FITC)-conjugated lectin showed that Ad-mSOD3 treatment increased the percentage of lectin+CD31+ vessels compared to Ad-C (Supplementary 4b), which implicates SOD3 directly in promoting tumor perfusion." (PMID 29422508, 2018). "To further study this SOD3/VEC association, we analyzed an independent validation cohort comprised of 87 CRC stage III and 19 non-tumor samples." (PMID 29422508, 2018). "As SOD3 regulated HIF-2α stability in mouse EC, we studied the expression of these two genes in the CRC TMA, using CD34 as a label of tumor-associated ECs; 55.4% of CD34+ ECs were SOD3 stained." (PMID 29422508, 2018). "Our results suggest that SOD3 improves tumor vascular function by augmenting HIF-2α-dependent VEC expression, probably by increasing NO availability and thus inhibition of PHD activity." (PMID 29422508, 2018). "Here, the authors show that SOD3 re-expression enhances doxorubicin delivery and effects through normalization of tumour vasculature via the HIF-2a/VE-cadherin pathway." (PMID 29422508, 2018). "Owing to the ability of Ad-mSOD3 to infect both tumor and stromal cells, SOD3 production was distributed homogeneously throughout the tumor parenchyma." (PMID 29422508, 2018). "A total of 76% of FITC-lectin+ structures in WT tumors (n = 46) showed more intense DAR-1 staining than in adjacent parenchyma, whereas strong DAR-1 staining was seen in only 50% of SOD3−/− tumor vessels (n = 34; p = 0.016, Pearson’s χ2)." (PMID 29422508, 2018). "PTC and FTC tumours presented a group of common dysregulated proteins including SOD3, ISLR, biotinidase, polymerase I and transcript release factor (cavin-1), TFF3, alpha(B)-crystallin (CryAB), AGR2, tenascin and 14-3-3 gamma." (PMID 27025787, 2016). "The initial decreased growth phase was followed by faster tumor development and in vivo selection of cells, which contained moderately increased SOD3 mRNA expression levels compared to control cell-derived tumors." (PMID 27293512, 2016). "In part, VEGF-C promotes tumor progression via regulating Sod3, which can eliminate the excessive oxidative species generated when tumor cells are rapidly growing." (PMID 25358638, 2014). "For example, studies exist that show a protective role for Sod3 against chemical or hormone-induced tumor formation." (PMID 25358638, 2014).